OGA (O-GlcNAcase)
Diseases named in the same sentence as OGA in open-access papers (continued):
Sharing a sentence is not in itself a finding about the gene and the disease.
progressive supranuclear palsy (2 papers, 2020 to 2025). A rare late-onset neurodegenerative disease characterized by supranuclear gaze palsy, postural instability, progressive rigidity, and mild dementia. "OGA inhibitors have recently entered early clinical trials for the treatment of Progressive Supranuclear Palsy as O-GlcNAcylation of Tau blocks the pathological effects of phosphorylation and aggregation of Tau." (PMID 32349769, 2020).
adenoma (1 paper, 2015). A neoplasm arising from the epithelium. "Histological examination consistently showed larger adenomas in colonic sections of OGA+/− mice compared with OGA+/+ mice." (PMID 25915426, 2015).
atherosclerosis (1 paper, 2025). A disease characterized by the build-up of fatty material and calcium deposition in the arterial wall resulting in partial or complete occlusion of the arterial lumen. "Therapeutic strategies targeting glycosylation pathways, particularly O-GlcNAc transferase (OGT), and O-GlcNAcase (OGA), hold promise for addressing myocardial ischemia-reperfusion injury, diabetic cardiomyopathy, and atherosclerosis." (PMID 40458788, 2025).
cardiomyopathy (1 paper, 2023). A disease of the heart muscle or myocardium proper. "OGA transgenic hybridization improves heart damage caused by mitochondrial damage by restoring the activity of complex I. Excess O‐GlcNAcylation can lead to cardiomyopathy, in part because of energy deficiencies." (PMID 38116061, 2023). "The experiment also found that although the amount of OGT in the heart muscle of mice is increasing, if OGT is crossed with OGA transgenic mice, cardiomyopathy and premature death can be saved." (PMID 38116061, 2023).
Chronic colitis (1 paper, 2015). A chronic inflammatory disease of the large intestine (colon, cecum and rectum). "OGA+/−mice exhibited increased body weight loss and decreased survival rate during chronic colitis progression." (PMID 25915426, 2015).
Cognitive impairment (1 paper, 2019). Abnormal cognition is characterized by deficits in thinking, reasoning, or remembering. "The long-term treatment of 5xFAD mice with the selective OGA inhibitor leads to significant reductions in Aβ accumulation and blocks cognitive impairments in AD model mice, as has also been reported elsewhere." (PMID 31160541, 2019).
colonic adenomas (1 paper, 2014). "This supports the immunoblotting data, which showed simultaneously increased OGT and OGA in colonic adenomas." (PMID 25000257, 2014). "Although O-GlcNAcylation is elevated in colonic adenomas, we observed reduced tumorigenesis in OGA+/− mice, in which O-GlcNAcylation is constantly elevated." (PMID 25000257, 2014). "We observed that human colonic adenomas exhibit elevated O-GlcNAcylation, and increased levels of both OGT and OGA." (PMID 25000257, 2014).
esophageal squamous cell carcinoma (1 paper, 2012). Esophageal squamous cell carcinoma (ESCC) is a type of esophageal carcinoma (EC) that can affect any part of the esophagus, but is usually located in the upper or middle third. "The results indicated that OGT promoted O-GlcNAcation and played a more important role than OGA in esophageal squamous cell carcinoma, suggesting that in esophageal squamous cell carcinoma, OGT was the main protein responsible for O-GlcNAcation." (PMID 23554759, 2012).
fibrosarcoma (1 paper, 2022). A malignant mesenchymal fibroblastic neoplasm affecting the soft tissue and bone.
Hyperammonemia (1 paper, 2022). An increased concentration of ammonia in the blood. "Taken together, these results suggest that OGA is a druggable candidate for therapy of hyperammonemia." (PMID 36064721, 2022). "In conclusion, our data show that hepatic O-GlcNAcylation enhances CPS1 catalytic efficiency for ammonia and promotes ureagenesis, thus indicating OGA as a novel therapeutic agent for therapy of both genetic and acquired diseases resulting in hyperammonemia." (PMID 36064721, 2022). "In addition, we provided clinically relevant data supporting the efficacy of OGA inhibitors for therapy of hyperammonemia due to both genetic and acquired disorders." (PMID 36064721, 2022). "Together, these results suggest that pharmacological inhibition of OGA might be effective for therapy of hyperammonemia occurring in both inherited and acquired liver disorders." (PMID 36064721, 2022). "Moreover, liver OGT and OGA protein amounts were unchanged during hyperammonemia." (PMID 36064721, 2022). "Therefore, although long-term treatments might be associated with toxicity or reduced efficacy because of such regulatory loops, short-term OGA inhibition might still be effective for treatment of life-threatening acute hyperammonemia due to either inherited or acquired diseases." (PMID 36064721, 2022).
hyperlipidemia (1 paper, 2022). "These connections provide plausible paths by which hyperlipidemia may influence the protein expression or activity of OGT and OGA." (PMID 36111295, 2022).
insulinoma (1 paper, 2008). "Using X-ray crystallography, enzymology, and cell biological studies on an insulinoma cell line, we show that, whereas streptozotocin competitively inhibits O-GlcNAcase and induces apoptosis, its galacto-configured derivative no longer inhibits O-GlcNAcase, yet still induces apoptosis." (PMID 18721751, 2008).
Intellectual disability (1 paper, 2025). "OGT missense variants leading to intellectual disability are associated with a compensatory loss of OGA mRNA and protein, leading to the intriguing possibility that the resulting impairment of pHAT domain function could also contribute to the disease mechanisms." (PMID 41044083, 2025). "OGT missense variants leading to intellectual disability are associated with a compensatory loss of OGA mRNA and protein, raising the intriguing possibility that the resulting loss of the pHAT-associated functions may also contribute to the mechanisms underpinning this disease." (PMID 41044083, 2025).
intestinal tumor (1 paper, 2014). "In addition, OGA heterozygosity, which results in increased levels of O-GlcNAcylation, attenuated intestinal tumor formation in the Apcmin/+ background." (PMID 25000257, 2014).
laryngeal carcinoma (1 paper, 2015). Carcinoma that arises from the laryngeal epithelium. "In this context, further studies of the precise roles of OGT and OGA and understanding the regulatory mechanisms occurring in laryngeal cancer will be needed." (PMID 25315705, 2015). "A significant difference in OGT and OGA protein levels was noted in laryngeal cancer tissue compared with adjacent normal laryngeal mucosa (p = 0.0004 and p = 0.007, respectively)." (PMID 25315705, 2015). "It should be emphasized that in our study, hyper-O-GlcNAcylation levels in laryngeal cancer tissue compared with normal mucosa was associated with an increased level of both OGT and OGA proteins." (PMID 25315705, 2015). "Nine of the 22 pN0 laryngeal cancer samples (40.9 %) and all 10 (100 %) of the pN1–3 samples demonstrated positive expression of OGA." (PMID 25315705, 2015). "The next stage also investigated whether OGT and OGA proteins can potentially determine the pTNM classification features of laryngeal cancer, since the tumor stage is currently the only accepted prognostic marker." (PMID 25315705, 2015). "However, it should be emphasized that more advanced tumors (pT3–pT4, N1–3) were more commonly found to be positive in a quantitative densitometric analysis, and to have higher mean OGT and OGA protein levels, than less advanced laryngeal cancers." (PMID 25315705, 2015). "Similarly, the expression of OGA protein was noticed in 80 % (8/10) of poorly differentiated laryngeal cancers (grade 3), 58.3 % (7/12) of moderately differentiated tumors (grade 2) and 40 % (4/10) of well-differentiated (grade 1) laryngeal cancers." (PMID 25315705, 2015).
laryngeal tumor (1 paper, 2022). "OGA was reported to have a higher expression level in poorly differentiated laryngeal tumor cells and was associated with a poor prognosis." (PMID 35252174, 2022).
muscle atrophy (1 paper, 2025). The loss of muscle tissue due to inactivity or disease. "Analysis of the longer‐term efficacy of OGA inhibition in various skeletal muscle atrophy models including ageing or hindlimb unloading as well as the denervation‐induced muscle atrophy model will be required in the future." (PMID 40937539, 2025).
Neurodegeneration (1 paper, 2023). Progressive loss of neural cells and tissue. "The widespread availability of OGA inhibitors, most notably Thiamet-G, which can be obtained from a wide variety of commercial vendors, has enabled exploration of the therapeutic potential of OGA inhibition in various neurodegeneration disease models." (PMID 37918804, 2023).
proteinopathies (1 paper, 2024). "This perspective aims to highlight recent PET radiotracers developed for five emerging targets in proteinopathies (i.e., mHTT, BACE1, TDP-43, OGA, and CH24H)." (PMID 39185440, 2024).
Sepsis (1 paper, 2024). Sepsis is defined as life-threatening organ dysfunction caused by a dysregulated host response to infection. "A LPS-induced septic mouse model administrated with O-GlcNAcase (OGA) inhibitor thiamet-G (TMG) was used to assess the effects of O-GlcNAcylation on sepsis-associated vascular dysfunction and pyroptosis." (PMID 37962578, 2024). "Thus, in our investigation, we will employ OGA inhibitors to explore the role and underlying mechanisms of O-GlcNAc modification in sepsis-induced endothelial cell pyroptosis." (PMID 37962578, 2024).
Skeletal muscle atrophy (1 paper, 2025). The presence of skeletal muscular atrophy (which is also known as amyotrophy). "Thus, OGA inhibitors are drugs with high potential for clinical use and are considered to be potential treatments for skeletal muscle atrophy by targeting OGA." (PMID 40937539, 2025).
trauma (1 paper, 2021). "In our study, PUGNAc administration resulted not only in cell and chondroprotective effects but also in chondroanabolic effects after cartilage trauma, implying a positive effect by OGA-inhibition and subsequent accumulation of O-glycosylated proteins." (PMID 34298867, 2021).
viral infections (1 paper, 2023). "Therefore, targeting the activity of OGT or OGA using pharmacological inhibitors may constitute a potential therapy for viral infections, inflammatory diseases, and cancers." (PMID 36473120, 2023).
α-synucleinopathies (1 paper, 2025). "Pharmacological inhibition of OGA or OGT effectively alleviates or exacerbates α-syn aggregation, spreading, dopaminergic neuron degeneration, and neuroinflammation, which contribute to α-synucleinopathies in neurodegenerative diseases." (PMID 41146299, 2025).
cancer (60 papers, 2013 to 2026). A tumor composed of atypical neoplastic, often pleomorphic cells that invade other tissues. "OGA is known to be dysregulated in various cancers and is implicated in tumor progression, metastasis, and immune modulation." (PMID 40771411, 2025). "Despite these propitious findings, only a few systematic analyses of OGT/OGA-associated PPI networks have been reported in cancer models." (PMID 36291918, 2022). "Further experiments suggested that the activity of PKM2 was dysregulated by OGA complex-associated acetylation and O-GlcNAcylation under cancer-related high glucose conditions." (PMID 36291918, 2022). "Dysregulation of the sole enzymes responsible for O-GlcNAc cycling, O-GlcNAc transferase (OGT) and O-GlcNAcase (OGA), and the associated cellular O-GlcNAc profile is a common feature across nearly every cancer type." (PMID 36291918, 2022). "The profiling of OGT/OGA-associated PPIs in cancer cells typically apply affinity purification or proximity biotinylation coupled with quantitative LC-MS/MS analysis (AP-MS or BioID-MS)." (PMID 36291918, 2022). "In the future, novel mechanisms underlying the dysregulation of HBP enzymes and OGT/OGA will likely be identified in cancer as well." (PMID 35201498, 2021). "In rapidly dividing tissue, the loss of OGT or OGA is lethal, making both enzymes attractive cancer therapy targets." (PMID 33916244, 2021). "Dysregulations of the O-GlcNAcylation as well as aberrant expression of OGT and/or OGA have been observed in cancer where they are associated with increased cancer cell proliferation and survival, invasiveness, and metastasis." (PMID 33424836, 2020). "This is a prevailing mechanism of the abnormal OGT/OGA networks underlying cancer development, also in line with the fact that O-GlcNAcylation is essential for transcription and translation, which are often reprogramed in cancer." (PMID 36291918, 2022). "Notably, dysregulation of OGT, OGA, and the associated cellular O-GlcNAc profile is commonly detected in all cancers." (PMID 36291918, 2022). "Furthermore, OGA with point mutations in the pHAT domain showed aberrant protein interactions compared to wild-type OGA (see “Systematic analyses of OGT/OGA associated PPI networks in cancer” section below)." (PMID 36291918, 2022). "OGA has many roles in distinct biological processes, such as cancer and embryonic stem cells, but its precise regulatory mechanism is far from being understood." (PMID 40449592, 2025). "O-GlcNAc modification, catalyzed by OGT (introducer) and OGA (remover), is a significant posttranslational modification with a noted increase in cancer contexts." (PMID 38609495, 2024). "This suggests that O-GlcNAc cycling is important in promoting cell proliferation pathways in several cancer types where OGA and OGT were both upregulated." (PMID 38601153, 2024). "And ubiquitination can regulate O-GlcNAcylation mainly shows the function of regulating OGT and OGA, thereby affecting cancer therapeutics resistance." (PMID 39487556, 2024). "Small-molecule inhibitors of OGT or OGA have been developed to combat various types of cancers both in vitro and in vivo." (PMID 39178944, 2024). "Cancer cells usually have high OGT levels but low OGA expression levels, and elevated O-GlcNAcylation appears to be a general characteristic of cancer cells." (PMID 39178944, 2024). "Reinforcing this supposition are data describing the differential regulation of Ogt and Oga mRNA maturation in cancer models and a murine model in which OGA activity has been ablated." (PMID 37949223, 2023). "The expression of OGT is found to be increased in a wide variety of cancers whereas misexpression (both upregulation and downregulation) of OGA is also similarly reported." (PMID 37689115, 2023). "Increased O-GlcNAcylation and changes in OGT and/or OGA expression have been demonstrated in several types of cancer." (PMID 37110670, 2023).
cancer (continued). "We also discussed the potential of leveraging integrated approaches to dissect the molecular connections of OGT/OGA dysfunction and cancer phenotypes and manipulating their protein interactions as novel targets for anti-cancer therapeutic interventions." (PMID 36291918, 2022). "In this review, we highlighted recent progress on the structural characterization of OGT and OGA, as well as their emerging roles in protein interaction networks in several cancer models." (PMID 36291918, 2022). "As previously reported that aberrant PPIs underlie the etiology of cancer, decoding the molecular connections of dysregulated OGT/OGA–protein networks in cancer will be important for therapeutic innovations." (PMID 36291918, 2022). "O-GlcNAc cycling enzymes (OGT and OGA) regulate the functions of proteins in a broad range of cellular processes and their dysfunctions have been detected in many cancer types." (PMID 36291918, 2022). "Similar to OGT, we used TCGA, TIMER2.0, and TISIDB to investigate the prognostic influence, pathological features, and clinical relevance of OGA expression in 33 major human cancer types." (PMID 36104770, 2022). "After it specifically targeted cancer cells, upregulated OGA catalyzed GlcNAc removal, exposing Ser." (PMID 36394009, 2022). "On the other side, both up- and down-regulation of OGA protein levels have been observed in different types and grades of cancer." (PMID 36291918, 2022). "By integrating complementary approaches, the research in this area will aid in the identification of key protein contacts and functional modules derived from OGT/OGA that drive oncogenesis and will illuminate new directions for anti-cancer drug development." (PMID 36291918, 2022). "More interestingly, a significant correlation between the expression levels of OGT/OGA and the grade/stage of tumors or prognosis has been discovered, promoting mechanistic investigations of these enzymes in cancer." (PMID 36291918, 2022). "Many studies have investigated the effects of aberrant OGT/OGA expression on global O-GlcNAcylation activity in cancer cells." (PMID 36291918, 2022). "In cancer cells, OGA transcript levels displayed compensatory variations upon alterations in O-GlcNAc status, whereas augmenting overall cellular O-GlcNAc levels leads to decreased transcript and translational efficiency of OGT." (PMID 35887161, 2022). "In line with this, O-GlcNAcylation levels and importance vary among different tissue types and OGT and OGA expression have different impacts and roles in different cancer types." (PMID 35868563, 2022). "OGT and OGA expression levels have been assessed in patients and normal samples of major human cancers." (PMID 36104770, 2022). "Herein, we highlight recent studies on the structural features of OGT and OGA, as well as the emerging roles and molecular mechanisms of their aberrant PPIs in rewiring cancer networks." (PMID 36291918, 2022). "For O-GlcNAcylation, besides the regulation from metabolic flux, HBP enzymes, OGT and OGA are regulated by cancer-related pathways as well." (PMID 35201498, 2021). "In this review, we will first summarize how oncogenic signals regulate HBP enzymes, OGT and OGA in cancer." (PMID 35201498, 2021). "Low OGT activity promotes c-MYC degradation to maintain survival in low glucose of cancer cells that were killed when O-GlcNAcylation was increased by the OGA inhibitor PUGNAC." (PMID 34868034, 2021). "Atypical expression and activities of OGT and OGA have been reported in all human cancers studied thus far." (PMID 33916244, 2021). "Fatty acid synthase, which is overexpressed in many cancer types, can interact with OGA and inhibit its activity." (PMID 35201498, 2021). "Protein O-GlcNAcylation is regulated by the action of two antagonistic enzymes, O-GlcNAc transferase (OGT) and O-GlcNAcase (OGA), and different reports in the literature have shown that the O-GlcNAcylation is related to different types of cancer." (PMID 33902430, 2021).